TPMT (thiopurine S-methyltransferase)
Diseases named in the same sentence as TPMT in open-access papers (continued):
Sharing a sentence is not in itself a finding about the gene and the disease.
neutropenia (14 papers, 2014 to 2025). A decrease in the number of neutrophils found in the blood. "Previous studies on the influence of TPMT have focused on predicting toxicity in those with a TPMT deficiency (heterozygotes and homozygotes for the TPMT variant) at a high risk of severe neutropenia and other AEs, even at standard doses of AZA." (PMID 37959208, 2023). "Heterozygous TPMT*3C was significantly associated with severe neutropenia with an increased risk (OR, 4.17; 95% CI, 1.25–13.90); p = 0.014) during the first 8 weeks." (PMID 34442427, 2021). "Patients carrying the AG genotype of TPMT were significantly associated with neutropenia (ANC < 500 cell/mm3) compared with the AA genotype (OR, 4.17; 95% CI, 1.25–13.91, p = 0.014)." (PMID 34442427, 2021). "The clinical relevance of this finding relates to the fact that patients homogenous for low TPMT activity are at markedly greater risk for dose-related toxicity such as neutropenia during treatment with 6-mercaptopurine." (PMID 24795743, 2014). "The patients with low TPMT activity, as a result of the deposition of AZA metabolites in their bone marrow, represent a risk group for severe neutropenia." (PMID 40868544, 2025). "These included previous neutropenia, comorbidities and poor metaboliser based on TPMT/NUDT genotype±enzyme intermediate or low activity." (PMID 38199851, 2024). "Only 5 out of 21 patients with neutropenia (23.8%) were in the lower quartile in terms of TPMT activity value." (PMID 37892708, 2023). "AZA is metabolised by thiopurine S-methyltransferase (TPMT), and patients with low TPMT levels can develop severe neutropenia." (PMID 35441568, 2022). "The first review published in 2008, was aimed at determining the cost of thiopurine methyltransferase (TPMT) genotyping per averted case of neutropenia." (PMID 34600523, 2021). "Our conclusion that all patients with SSc were carriers of TPMT*3A instead of *3B or *3C is aligned with the fact that no severe side effects (e.g., myelosuppresion or neutropenia associated with thiopurine administration) were reported following the treatment with AZA." (PMID 37239884, 2023). "The pharmacogenomic biomarker for thiopurine methyltransferase (TPMT) has been studied extensively due to the drug’s serious side effects, such as neutropenia and myelosuppression." (PMID 31623616, 2019).
autoimmune disease (10 papers, 2015 to 2025). A disorder resulting from loss of function or tissue destruction of an organ or multiple organs, arising from humoral or cellular immune responses of the individual to their own tissue constituents. "A meta-analysis investigated the associations between TPMT polymorphisms and azathioprine-induced adverse events in patients with autoimmune diseases." (PMID 31387318, 2019). "Eleven published studies, with a total of 651 patients with autoimmune diseases, investigated associations between TPMT polymorphisms and AZA-induced ADRs, were included in this meta-analysis." (PMID 26633017, 2015). "The finding of a significant association may become indirect evidence for pretesting TPMT genotype before commencing AZA therapy in patients with autoimmune diseases." (PMID 26633017, 2015). "A total of 83 patients with IBD and other autoimmune diseases had their TPMT and NUDT15 genotypes analysed." (PMID 41300822, 2025). "An increased risk of thiopurine toxicity has been observed in patients with a TPMT deficiency in various conditions beyond IBD, such as hematologic malignancies, transplantation, and autoimmune diseases." (PMID 37959208, 2023). "Studies that compared TPMT polymorphisms with-ADRs and without-ADRs in patients with autoimmune diseases were included." (PMID 26633017, 2015). "Interestingly, in our hospital, some physicians use TPMT genotyping for the prescription of thiopurines in the management of patients with autoimmune diseases, but others do not, arguing that they do not consider this biomarker useful for the selection and titration of thiopurine doses." (PMID 37623459, 2023).
pancreatitis (9 papers, 2015 to 2025). Inflammation of the pancreas. "It is important to note that, despite having a normal TPMT level, patients are still at risk for myelotoxicity, hepatitis, and pancreatitis due to mechanisms unrelated to TPMT levels." (PMID 27446822, 2016). "Of the 62 patients with thiopurine-induced pancreatitis, 2 (3.3%) were TPMT polymorphisms positive, while 116 (7.7%) of the 1500 patients without pancreatitis were TPMT polymorphisms positive." (PMID 25799415, 2015). "Adverse drug reactions such as influenza-like symptoms, rash, and pancreatitis are not explained by TPMT deficiency." (PMID 38399389, 2024). "For example, a Dutch study did define a genetic passport that included several loci (TPMT, NUDT15, HLA-DQA1*02:01-HLA-DRB1*07:01, and HLA-DQA1*05) associated with toxic effects from thiopurines (i.e., myelosuppression and pancreatitis) and anti-TNFα mABs (i.e., immunogenicity)." (PMID 33628180, 2020). "Our meta-analysis demonstrated an association of TPMT polymorphisms with overall thiopurine-induced ADRs and bone marrow toxicity, but not with hepatotoxicity, pancreatitis, flu-like symptoms, gastric intolerance and skin reactions." (PMID 25799415, 2015). "Although we tried to analyze the association between TPMT polymorphisms and all the ADRs induced by thiopurine, the heterogeneous definitions of BMT, hepatotoxicity and pancreatitis are indeed problematic, indicating that the results of this meta-analysis should be interpreted with caution." (PMID 25799415, 2015). "Several studies have shown that the absence of TPMT activity may be associated with increased risk for drug-related toxicity of patients, including myelosuppression, hepatotoxicity, and pancreatitis." (PMID 34322485, 2021). "Interestingly, pancreatitis occurred more frequently in the low-dose treatment group, which is consistent with the current hypothesis that thiopurine-associated pancreatitis is not related to the TPMT enzyme pathway and may be an idiosyncratic reaction." (PMID 27446822, 2016). "Pancreatitis is a dose-independent ADR, which seems to be independent of the accumulation of thiopurine metabolites and TPMT polymorphisms." (PMID 25799415, 2015). "However, the previously published study only investigated the association of TPMT polymorphisms on thiopurine-induced BMT, hepatotoxicity and pancreatitis, not including all the common thiopurine-induced ADRs." (PMID 25799415, 2015).
Crohn disease (8 papers, 2016 to 2024). A gastrointestinal disorder characterized by chronic inflammation involving all layers of the intestinal wall, noncaseating granulomas affecting the intestinal wall and regional lymph nodes, and transmural fibrosis. "In children and adults with Crohn’s disease, co-prescribing allopurinol with 6MP blocks the activity of thiopurine methytransferase (TPMT), reducing 6MMP and improving its tolerance." (PMID 30828444, 2019). "Nine patients out of 100 (Crohn’s disease- 67, ulcerative colitis- 23 and IBDU-10) had known TPMT mutations associated with deficient enzyme activity." (PMID 27703193, 2016).
myelosuppression (8 papers, 2015 to 2025). Myelosuppression or bone marrow suppression is a condition in which bone marrow activity is decreased, resulting in fewer red blood cells, white blood cells, and platelets. "This is in contrast to the Caucasians, where common thiopurine methyltransferase (TPMT) variants were shown to be associated with 6-MP-induced myelosuppression." (PMID 32481505, 2020). "In Japanese individuals, the ITPA gene polymorphism may be more influential compared with the TPMT polymorphism in inducing thiopurine-induced myelosuppression." (PMID 26360046, 2015). "Literature reports indicate that genetic variants, primarily in the enzymes thiopurine S-methyltransferase (TPMT) and nudix hydrolase 15 (NUDT15), are associated with an increased risk of developing myelosuppression, conferring up to twice the risk." (PMID 39539906, 2024). "Among four patients who developed myelosuppression, none had low TPMT activity; one had intermediate, and three had high activity." (PMID 41153516, 2025). "Myelosuppression is more common in those with low levels of the enzyme thiopurine S-methyltransferase (TPMT) and measurement of TPMT is recommended but not compulsory prior to starting azathioprine." (PMID 27446862, 2016).
Pancytopenia (6 papers, 2014 to 2025). An abnormal reduction in numbers of all blood cell types (red blood cells, white blood cells, and platelets). "Azathioprine, a purine antimetabolite and immunosuppressive drug, is known to cause myelosuppression and pancytopenia, particularly in those with reduced levels of thiopurine methyltransferase (TPMT) activity." (PMID 40230407, 2025). "However, one patient with complete TPMT deficiency and two heterozygous carriers developed pancytopenia, supporting the need for TPMT testing to avoid potentially fatal myelotoxicity." (PMID 41153516, 2025). "The longest duration of pancytopenia was 137 days in an 8-year-old boy with ALL who was homozygous for TPMT *3A/*3A." (PMID 25541649, 2014). "Patients homozygous or compound heterozygous for a nonfunctional TPMT allele develop pancytopenia 2 to 4 weeks after starting oral 6-MP and recover within 2-6 weeks." (PMID 25541649, 2014). "As a consequence of inhibiting TPMT, 6MP is shunted toward the production of 6-thioguanine nucleotide (6TGN), which will result in pancytopenia if the dose of 6MP is not reduced." (PMID 30828444, 2019).
hearing loss (4 papers, 2012 to 2020). "Among other candidate genes, thiopurine methyltransferase (TPMT) is considered a critical gene for susceptibility to cisplatin-induced hearing loss in a pharmacogenetic guideline." (PMID 32939381, 2020). "Because of that, the Food and Drug Administration (FDA) had issued a special precaution on cisplatin drug labels stating that individuals with allele TPMT*3B and TPMT*3C (*3A is haplotype of *3B and *3C) are at a higher risk of hearing loss." (PMID 27618021, 2016). "With this largest meta-analysis performed to date, we show that the influence of TPMT and COMT on the development of cisplatin-induced hearing loss may be less important than previously suggested." (PMID 25551397, 2014). "With the largest meta-analysis performed to date we show that the influence of TPMT and COMT on the development of cisplatin-induced hearing loss may be less pronounced than previously suggested." (PMID 25551397, 2014). "It has been suggested that genetic variants in the genes encoding thiopurine S-methyltransferase (TPMT) and catechol O-methyltransferase (COMT) can predict the development of cisplatin-induced ototoxicity and may explain interindividual variability in sensitivity to cisplatin-induced hearing loss." (PMID 25551397, 2014).
Hepatitis (4 papers, 2016 to 2021). Inflammation of the liver. "The AASLD also suggests a period of a 2-week observation before the initiation of AZA in order to confirm the patient’s steroid responsiveness and to evaluate the status of thiopurine-S methyltransferase (TPMT) to avoid AZA-induced hepatitis." (PMID 34441353, 2021).
Cirrhosis (3 papers, 2019 to 2025). A chronic disorder of the liver in which liver tissue becomes scarred and is partially replaced by regenerative nodules and fibrotic tissue resulting in loss of liver function. "Patients with normal TPMT activity can still develop dose-dependent toxicities such as cytopenia, which are more commonly present in patients with cirrhosis." (PMID 38396421, 2024). "In the context of compensated cirrhosis, TPMT activity should be assessed and after 2 weeks; azathioprine can be initiated at 50–150 mg daily." (PMID 38396421, 2024).
lymphoma (3 papers, 2019 to 2023). A malignant (clonal) proliferation of B- lymphocytes or T- lymphocytes which involves the lymph nodes, bone marrow and/or extranodal sites. "For blood, immune system and liver-based cancers, B-cell leukemias and lymphomas (BCL), Tyrosine-protein kinase (ABL), cluster of differentiate (CD) 20 antigen, CD 30, and Thiopurine methyltransferase (TPMT) are used." (PMID 36832253, 2023).
Thrombocytopenia (3 papers, 2021 to 2025). A reduction in the number of circulating thrombocytes. "A significant association of thrombocytopenia (PLT < 50,000 cell/mm3) was identified in the patients of the TPMT AG genotype compared to the AA genotype with an OR of 4.20 (95% CI, 1.25–14.12, p = 0.014)." (PMID 34442427, 2021). "Additionally, we also found a significant association between TPMT*1/*3C and 6-MP-induced-thrombocytopenia (PLT < 25,000 cell/mm3) during 24 weeks of maintenance therapy when compared with TPMT*1/*1 (OR 4.20; 95% CI: 1.25–14.12; p = 0.014)." (PMID 34442427, 2021).
agranulocytosis (2 papers, 2023 to 2024). "Still, isolated agranulocytosis is rare except with the usage of azathioprine which is due to either thiopurine methyltransferase (TPMT) or the enzyme nudix hydrolase 15 (NUDT 15) mutations." (PMID 39463872, 2024). "As previously outlined, of particular importance is the search for the mutation of TPMT before starting AZA, to prevent the appearance of secondary leukopenia/agranulocytosis." (PMID 36979048, 2023).
anemia (2 papers, 2013 to 2025). A reduction in the number of red blood cells, the amount of hemoglobin, and/or the volume of packed red blood cells. "Iron-deficiency anemia and diabetes mellitus were associated with a very high TPMT activity (p = 0.0004 and p = 0.0015, respectively)." (PMID 24385893, 2013). "We discovered an association between a very high TPMT activity and nutritional anemia and diabetes." (PMID 24385893, 2013).
autoimmune hepatitis (2 papers, 2019 to 2021). Hepatitis caused by autoantibodies. "This study aimed to investigate the influence of TPMT*3C, ITPA, NUDT15, and 6-thioguanine nucleotides (6-TGN) on azathioprine (AZA)-induced myelosuppression in Southwest China patients with autoimmune hepatitis (AIH)." (PMID 33846471, 2021).
childhood cancer (2 papers, 2016 to 2023). "Currently, the most well‐studied pharmacogene with personalized prescribing in pediatric childhood cancer therapy is thiopurine methyltransferase (TPMT)." (PMID 38013228, 2023).
deafness (2 papers, 2018 to 2023). An inherited or acquired condition characterized by the complete loss of the ability to hear from one or both ears. "We did not include the SNPs in the following genes: ACYP2 (coding for an acylphosphatase), SLC31A1 gene coding for the copper transport protein 1, SLC22A2 coding for the organic cation transport protein 2, megalin, TPMT and COMT and Mendelian deafness gene." (PMID 30112115, 2018). "Thiopurine methyltransferase (TPMT), glutathione-S-transferase pi (GSTP1), cation transporters solute carrier family 22 member 2 (SLC22A2), and numerous deafness-related genes (otospiralin OTOS) have been observed to be associated with cisplatin ototoxicity in some genetics studies." (PMID 37323582, 2023).
diabetes (2 papers, 2013 to 2022). "For instance, GCs should be avoided for those who are overweight and/or have diabetes, MTX should be avoided for those with chronic kidney disease, and AZA should be avoided for those with TPMT deficiency." (PMID 35855576, 2022).
idiopathic pulmonary fibrosis (2 papers, 2023). Idiopathic pulmonary fibrosis (IPF) is a nonneoplastic pulmonary disease that is characterized by the formation of scar tissue within the lungs in the absence of any known cause. "In 2010, researchers concluded that genotyping for TPMT in idiopathic pulmonary fibrosis (IPF) could be cost-effective if the incidence of intermediate or poor metabolizers exceeded 12.5%." (PMID 37623459, 2023).
lupus (2 papers, 2021 to 2025). "The most prescribed tests were rheumatoid factor, anti-CCP antibodies, antibodies panels for lupus, myositis and scleroderma, HLA-B27, HLA-B51, HLA-B*5801, TPMT and G6PD deficiency." (PMID 34839831, 2021).
lymphopenia (2 papers, 2022 to 2025). Reduction in the number of lymphocytes. "An underlying homozygous TPMT (thiopurine S-methyltransferase) deficiency with subsequent insufficient degradation of 6-MP was identified as contributory for the development of a distinct lymphopenia leading to EBV LPD." (PMID 35601437, 2022). "Further studies are then needed to assess the relationship between lymphopenia and GST and TPMT activity." (PMID 40868544, 2025).
melanoma (2 papers, 2016 to 2025). A malignant, usually aggressive tumor composed of atypical, neoplastic melanocytes. "Moreover, the rest of SASP-related genes recruited in our risk-scoring model including HLA-B, TPMT, ATM, CD59, TRIM21, and ASPRV1 have not been well studied in melanoma, indicating their potential of novel therapeutic target." (PMID 40864319, 2025).
myositis (2 papers, 2021 to 2024). "Azathioprine, titrated up to 100 mg over a year, was next tested and produced satisfactory results in myositis suppression despite her low thiopurine methyltransferase (TPMT) enzyme status." (PMID 39165465, 2024).
Obesity (2 papers, 2014 to 2019). Accumulation of substantial excess body fat. "The genes NPY and GABRA2 have been previously found associated with obesity and food intake, being involved in multiple central nervous system functions regulation, while TPMT has an important role in drug metabolism." (PMID 24548628, 2014).
ovarian carcinoma (2 papers, 2014 to 2022). A malignant neoplasm originating from the surface ovarian epithelium. "Furthermore, a recent study demonstrated that functional TPMT variants were associated with progression-free survival in cisplatin-based chemotherapy outcomes in ovarian cancer." (PMID 25551397, 2014).
pancreatic cancer (2 papers, 2020 to 2023). "Similarly, a damaging thiopurine methyltransferase (TPMT) variant was used in order to exclude a cisplatin therapy in a patient with pancreatic cancer, as reduced metabolism of the drug due to the variant would lead to enhanced toxicity for that patient." (PMID 32411592, 2020). "TPMT expression is reported to be different between normal and pancreatic cancer cells, and knockdown of TPMT sensitizes Panc1 cells to 6-thioguanine." (PMID 37202783, 2023).
acute leukemia (1 paper, 2025). A clonal (malignant) hematopoietic disorder with an acute onset, affecting the bone marrow and the peripheral blood. "Polymorphisms in genes such as TPMT (e.g., 3A, 3C) and NUDT15 (e.g., rs116855232) are strongly associated with severe myelotoxicity in patients with acute leukemia treated with thiopurines, such as mercaptopurine and thioguanine." (PMID 41301675, 2025).
astrocytoma (1 paper, 2015). "One child (TPMT wild‐type), aged 4 years at diagnosis, was diagnosed with a brain tumour (grade 2 astrocytoma) 10·3 years after diagnosis." (PMID 25441457, 2015).
atrial fibrillation (1 paper, 2023). A disorder characterized by an electrocardiographic finding of a supraventricular arrhythmia characterized by the replacement of consistent P waves by rapid oscillations or fibrillatory waves that vary in size, shape and timing and are accompanied by an irregular ventricular response. "SNPs located near the neighboring genes TPMT and NHLRC1 were associated with decreased risk of atrial fibrillation, autoimmune and inflammatory diseases, and increased risk of sleep disorders." (PMID 37076473, 2023).
bone marrow failure (1 paper, 2015). "TPMT deficiency (1 in 300 individuals) is associated with bone marrow failure when such patients are treated with standard doses of thiopurine drugs; a less severe myelosuppression can develop in TPMT heterozygotes (‘intermediate’ activity, 11% of subjects)." (PMID 25441457, 2015).
colitis (1 paper, 2017). Inflammation of the colon. "A daily AZA dose of 2–3 mg/kg for individuals with wild-type TPMT is recommended by the Clinical Pharmacogenetics Implementation Consortium guidelines, and 1.5 to 2.5 mg∙kg-1∙d-1 is recommended by the European Crohn’s and Colitis Organization." (PMID 29206869, 2017).